MRTFA (myocardin related transcription factor A)
Description:
Transcription coactivator that associates with the serum response factor (SRF) transcription factor to control expression of genes regulating the cytoskeleton during development, morphogenesis and cell migration. The SRF-MRTFA complex activity responds to Rho GTPase-induced changes in cellular globular actin (G-actin) concentration, thereby coupling cytoskeletal gene expression to cytoskeletal dynamics. MRTFA binds G-actin via its RPEL repeats, regulating activity of the MRTFA-SRF complex. Activity is also regulated by filamentous actin (F-actin) in the nucleus.
Synonyms: MRTF-A; KIAA1438; MAL; MKL1; BSAC; MKL
Tractability: PROTAC: ubiquitination databases record sites on it.
Gene: Protein-coding gene on chromosome 22 (40,410,281 to 40,636,719, reverse strand). Ensembl gene ENSG00000196588.
Subcellular location: Cytoplasm; Nucleus
Subcellular location (Human Protein Atlas): Nucleoplasm; Cytosol; Nuclear membrane
Pathways (Reactome):
Metabolism of proteins: SUMOylation of transcription cofactors
Signal Transduction: RHO GTPases Activate Formins
Gene Ontology:
Molecular function: actin binding; leucine zipper domain binding; protein binding; transcription coactivator activity; actin monomer binding
Biological process: positive regulation of miRNA transcription; positive regulation of transcription by RNA polymerase II; smooth muscle cell differentiation; wound healing, spreading of cells; actin cytoskeleton organization
Cellular component: cytoplasm; nuclear membrane; nucleoplasm; nucleus; cytosol
Genetic constraint (gnomAD): Loss-of-function variants: 20 observed, 74.79 expected, observed/expected ratio (o/e) 0.27, 90% interval 0.19 to 0.39. The synonymous counts are far from expectation, so gnomAD's model fits this gene poorly and the ratio says little. Missense variants: 1,196 observed, 1,190.2 expected, observed/expected ratio (o/e) 1, 90% interval 0.96 to 1.05. Synonymous variants: 657 observed, 527.91 expected, observed/expected ratio (o/e) 1.24, 90% interval 1.17 to 1.33.
Homologues: Orthologues: macaque MRTFA (97% identical), chimpanzee MRTFA (92% identical), dog MRTFA (90% identical), rat Mrtfa (87% identical), mouse Mrtfa (79% identical), pig MRTFA (65% identical), guinea pig MRTFA (63% identical), rabbit MRTFA (52% identical), tropical clawed frog mrtfa (47% identical), zebrafish mrtfab (46% identical), zebrafish mrtfaa (44% identical), Caenorhabditis elegans pqn-62 (19% identical), and 1 more. Paralogues in human: MRTFB (45% identical), MYOCD (32% identical).
Diseases named in the same sentence as MRTFA in open-access papers:
MRTFA is named in the same sentence as 154 diseases in open-access papers, as found by Europe PMC text mining. Sharing a sentence is not in itself a finding about the gene and the disease. The quoted sentences say what the papers report.
breast carcinoma (49 papers, 2014 to 2025). "Overexpression of myocardin-related transcription factor A significantly promotes the migration of breast cancer cells through reverse transcription of MYL9 and CYR61 genes." (PMID 34974798, 2022). "MRTFA plays an important role in the interaction pathways in breast cancer." (PMID 38397135, 2024). "A recent study suggested that up-regulation of myocardin-related transcription factor A (MRTF-A) by E2 might be a switch between proliferation-promoting and metastasis-promoting functions of E2 in ER positive breast cancer cells." (PMID 27160081, 2016). "For example, the interaction between MRTFA and STAT3 promotes the migration of breast cancer cells, and the crosstalk of MRTF-YAP is required for cancer cell migration and metastasis." (PMID 37982489, 2023). "In breast cancer, MYL9 is activated by myocardin-related transcription factor-A and promotes MCF-7 cell migration." (PMID 36589754, 2022). "MRTFA was enriched in BLBC and was positively correlated with MaSC/progenitor cell signature and IL6 expression, whereas MRTFB was enriched in luminal-type breast cancer and was negatively correlated with MaSC/progenitor cell signature and IL6 expression." (PMID 26671411, 2015). "Among those genes, most were described in the functional analyses of previously published MD GWAS32,47,48, such as MKL1/MRTFA (rs73169097 – negative ‘null’ cluster SNP) and MTMR11 (rs11205303), both of which have dense phenotype-increasing effect but are protective against breast cancer." (PMID 38740751, 2024).
acute megakaryoblastic leukemia (21 papers, 2012 to 2025). Acute megakaryoblastic leukemia (AMKL) is a form of acute myeloid leukemia (AML) that occurs predominantly in childhood and particularly in children with Down syndrome (DS-AMKL). "In conclusion, we describe a case of acute megakaryoblastic leukemia (AMKL) with RBM15::MRTFA fusion associated with severe hepatic fibrosis and portal hypertension that resolved with chemotherapy." (PMID 39281382, 2024). "MRTFA is associated with acute megakaryocytic leukemia, acts as a coactivator of SRF, and inhibits activation of caspases, which suppresses apoptosis." (PMID 31548358, 2019). "MKL1, also called MRTF-A (myocardin-related transcription factor-A) or MAL (megakaryocytic acute leukemia), is a transcriptional co-regulator expressed in many cell types." (PMID 33692789, 2021). "Extramedullary involvement of acute myeloid leukemia (AML), aka myeloid sarcoma, is a rare phenomenon in acute megakaryoblastic leukemia with RBM15:: MRTFA(MKL1) fusion, which might mimic non-hematologic malignancies." (PMID 38374236, 2025).
atherosclerosis (12 papers, 2017 to 2022). A disease characterized by the build-up of fatty material and calcium deposition in the arterial wall resulting in partial or complete occlusion of the arterial lumen. "It has been previously shown that MRTFA and its related family members MRTFB and myocardin are regulated in vascular injury and atherosclerosis models." (PMID 33597582, 2021).
liver fibrosis (12 papers, 2016 to 2025). "Previously, our investigation has led to the discovery of myocardin-related transcription factor A (MRTF-A) as a key modulator of HSC activation and liver fibrosis." (PMID 28548935, 2017).
pulmonary fibrosis (12 papers, 2014 to 2026). Chronic progressive interstitial lung disorder characterized by the replacement of the lung tissue by connective tissue, leading to progressive dyspnea, respiratory failure, or right heart failure. "ECM stiffness and mechanical signaling (i.e., RhoA/ROCK, myocardin-related transcription factor-A [MRTF-A], and YAP/TAZ) promote pulmonary fibrosis via TRPV4-related signaling and others." (PMID 37518181, 2023). "TGF-β1 promotes the nuclear localization of myocardin-related transcription factor-A (MRTF-A), which regulates the differentiation and survival of fibroblasts, resulting in enhanced lung fibrosis." (PMID 30909462, 2019).
hepatocellular carcinoma (11 papers, 2013 to 2026). A malignant tumor that arises from hepatocytes. "LPA also affects senescence, as in hepatocellular carcinoma, LPA activates LPAR1, which interacts with myocardin-related transcription factor A (MRTF-A) and filamin A to trigger actin polymerisation and protect against oncogene-induced senescence." (PMID 38607068, 2024). "Myocardin-related transcription factor A (MRTF-A) is a coactivator of serum response factor (SRF), which regulates the expression of genes involved in cell proliferation, migration, and differentiation and has been implicated in hepatocellular carcinoma (HCC) progression." (PMID 39262570, 2024). "Furthermore, Megakaryoblastic leukemia 1 (MKL1), alternatively known as MRTF-A (myocardin-related transcription factor A), regulates endothelial-to-mesenchymal transition and oncogene-induced senescence during pathogenesis of hepatocellular carcinoma and other liver disorders." (PMID 34742274, 2021). "Myocardin-related transcription factor A (MRTF-A) is a coactivator of serum response factor (SRF), which regulates the expression of genes involved in cell proliferation, migration, and differentiation and plays an important role in hepatocellular carcinoma (HCC) growth." (PMID 39262570, 2024).
melanoma (11 papers, 2015 to 2025). A malignant, usually aggressive tumor composed of atypical, neoplastic melanocytes. "Recent mechanistic investigations have clarified that pirin acts as a transcriptional co-regulator in melanoma cells, directly engaging with MRTF-A (myocardin-related transcription factor A)." (PMID 40740997, 2025). "The phenotypic shift induced in melanoma cells by these double treatments is dependent on YAP1 (yes-associated protein 1)- and MRTFA (Myocardin Related Transcription Factor A)-activity in resistant melanoma cells." (PMID 35558554, 2022). "The importance of MRTFA as a resistance factor has been also investigated in RAC1P29S-mutated cells, the third most common mutation in melanoma after BRAFV600E and NRASQ61." (PMID 32466585, 2020). "Together with YAP1/TAZ, MRTFA is another central mediator of mechanical stimuli also involved in the acquisition of MAPKi resistance in melanoma cells." (PMID 32466585, 2020). "The role of MRTFA in resistance has been especially studied in MITFlow/RTKhigh-resistant melanoma cells that acquire key features of CAFs, such as ECM remodeling activities." (PMID 32466585, 2020). "Cell‐autonomous ECM deposition and remodeling abilities adopted by melanoma cells after MAPKi treatment result in cross‐linked collagen matrix and tumor stiffening fostering a feedforward loop dependent on the mechanotransducers YAP and MRTFA and leading to therapy resistance." (PMID 35156321, 2022). "Expression of miR‐143‐3p and miR‐145‐5p in therapy‐naïve melanoma cells enhanced YAP and MRTFA nuclear localization as shown by immunofluorescent staining." (PMID 35156321, 2022). "Similarly, high levels of RhoA signaling, coupled with elevated activation of MRTFA and YAP1, promotes BRAFi resistance in dedifferentiated melanoma cell lines characterized by a decreased expression of melanocyte lineage genes." (PMID 32466585, 2020).
leukemia (9 papers, 2012 to 2025). A malignant (clonal) hematologic disorder, involving hematopoietic stem cells and characterized by the presence of primitive or atypical myeloid or lymphoid cells in the bone marrow and the blood. "MKL/MRTF molecules, MKL1/MRTFA [also termed megakaryocytic leukemia (MAL), basic, SAP, and coiled-coil domain (BSAC)] and MKL2/MRTFB (also termed MAL16), were identified following the discovery of myocardin." (PMID 34795561, 2021).
cardiac hypertrophy (8 papers, 2011 to 2025). "In the present study, we investigated the cardiomyocyte-specific role of myocardin-related transcription factor A (MRTF-A) in angiotensin-II (Ang-II)-induced cardiac hypertrophy and the underlying mechanism." (PMID 33015041, 2020). "Overall, our results show that progerin expression in ECs leads to defects in nucleocytoskeletal coupling, in flow stress response, and in MRTFA/eNOS signaling, which in turn induce profibrotic changes, cardiovascular stiffening, and cardiac hypertrophy." (PMID 30422822, 2019). "Myocardin-related transcription factor A (MRTF-A) potentially regulated macrophage trafficking, contributing to the pathogenesis of cardiac hypertrophy by activating integrin B2 (ITGB2) transcription." (PMID 40585349, 2025).
Immunodeficiency (5 papers, 2019 to 2022). Failure of the immune system to protect the body adequately from infection, due to the absence or insufficiency of some component process or substance. "Moreover, mutations in β-actin and the actin sensor Myocardin Related Transcription Factor A (MRTF-A)/Megakaryoblastic leukemia 1 protein (MKL1) lead to severe immunodeficiencies with poorly functional immune cells." (PMID 34422807, 2021).
Obesity (5 papers, 2015 to 2022). Accumulation of substantial excess body fat. "MRTFA KO mice are protected from HFD-induced obesity and insulin resistance, demonstrating that MRTFA is a negative regulator of beige cell formation." (PMID 26322018, 2015). "Obesity would induce hypoxia in adipose tissue, which creates a diseased phenotype by inhibiting adipocyte maturation and inducing actin stress fiber formation facilitated by myocardin-related transcription factor A (MRTF-A/MKL1) nuclear translocation and the induced RhoA signaling." (PMID 36589802, 2022). "Strategies to inhibit TGF-β signaling (SMADs and MRTFA) might limit the negative consequences of obesity by directly retaining the metabolic functions of adipocytes." (PMID 32047213, 2020).
osteosarcoma (5 papers, 2020 to 2025). A usually aggressive malignant bone-forming mesenchymal neoplasm, predominantly affecting adolescents and young adults. "A stiff matrix induces nuclear localization of myocardin-related transcription factor A (MRTF-A) in osteosarcoma cells and promotes EMT and migration of osteosarcoma cells." (PMID 35205794, 2022). "Matrix stiffness regulates EMT via cytoskeletal remodeling and MRTFA translocation in osteosarcoma." (PMID 37007130, 2023).
renal fibrosis (5 papers, 2015 to 2023). A final common manifestation of a wide variety of chronic kidney diseases characterized by glomerulosclerosis and tubulointerstitial fibrosis. "Previous studies have revealed that loss of myocardin-related transcription factor A (MRTF-A) reduces renal fibrosis." (PMID 37121967, 2023). "Previous studies have demonstrated that systemic deficiency in myocardin-related transcription factor A (MRTF-A) attenuates renal fibrosis in mice." (PMID 37121967, 2023).
acute myeloid leukemia (4 papers, 2017 to 2025). Acute myeloid leukemia (AML) is a group of neoplasms arising from precursor cells committed to the myeloid cell-line differentiation. "Based on the evaluation of all these findings together, acute myeloid leukemia with RBM15::MRTFA(MKL1) fusion diagnosis was made, and the diagnosis for soft tissue lesion was revised to myeloid sarcoma." (PMID 38374236, 2025). "RBM15::MRTFA is among the recurring translocations defining acute myeloid leukemia." (PMID 38374236, 2025).
schizophrenia (3 papers, 2018 to 2022). A major psychotic disorder characterized by abnormalities in the perception or expression of reality. "The analysis of large-scale schizophrenia cohort studies identified a genome-wide significant schizophrenia risk locus at 22q13.1 and demonstrated that seven single nucleotide polymorphisms (SNPs) of the MKL1/MRTFA gene had the most significant association with schizophrenia." (PMID 34795561, 2021).
asthma (2 papers, 2020). "For example, in an asthma mice model, TRPV4 activation in the membrane promotes an increase in transforming growth factor- beta 1 (TGF-β1) through a signaling pathway involving PI3K and leads to stimulation of the myocardin-related transcription factor A (MRTF-A), which depends on Rho/myocardin." (PMID 32481620, 2020).
cardiomyopathy (2 papers, 2012 to 2022). A disease of the heart muscle or myocardium proper. "Here, we show that in muscle cells carrying a cardiomyopathy-causing LMNA mutation, phospho(T25)-cofilin-1 binds to myocardin-related transcription factor A (MRTF-A) in the cytoplasm, thus preventing the stimulation of serum response factor (SRF) in the nucleus." (PMID 36550158, 2022).
acute leukemia (1 paper, 2020). A clonal (malignant) hematopoietic disorder with an acute onset, affecting the bone marrow and the peripheral blood. "MKL1, also known as megakaryocytic acute leukemia (MAL), basic SAP and coiled-coil domain containing protein (BSAC) or myocardin-related transcription factor A (MRTF-A), is one of three members of the myocardin family." (PMID 32408494, 2020).
adenovirus infection (1 paper, 2022). "After adenovirus infection, the localization of the MRTFA-GFP fusion protein was analyzed in cardiomyocytes that were cultured in a serum-free DMEM medium for 24 h." (PMID 35806398, 2022).
hepatoblastoma (1 paper, 2025). Hepatoblastoma (HB) is a malignant hepatic tumor and is the most common pediatric liver cancer. "There are a few reported cases of myeloid sarcoma related to AML with RBM15::MRTFA(MKL1) fusion in the literature, which mimic non-hematologic malignancies like neuroblastoma, hepatoblastoma, or small round blue cell tumor, thus the differential diagnosis may be challenging." (PMID 38374236, 2025).
left ventricular hypertrophy (1 paper, 2021). Enlargement of the LEFT VENTRICLE of the heart. "These transgenic mice exhibited deregulated activity of a major cardiac transcription factor termed mechanoresponsive myocardin-related transcription factor-A (MRTFA) and developed myocardial and perivascular fibrosis, left ventricular hypertrophy, and premature death." (PMID 33507327, 2021).
mesenchymal tumor (1 paper, 2025). "In conclusion, AML with RBM15::MRTFA(MKL1) fusion can initially present as a soft tissue lesion in children and may lead to misdiagnosis of the malignant mesenchymal tumor." (PMID 38374236, 2025).
myeloid sarcoma (1 paper, 2025). A tumor mass composed of myeloblasts or immature myeloid cells. "Based on these findings, myeloid sarcoma/AML with RBM15::MRTFA(MKL1) fusion diagnosis was made." (PMID 38374236, 2025).
Skeletal muscle atrophy (1 paper, 2021). The presence of skeletal muscular atrophy (which is also known as amyotrophy). "Emerging evidence also suggests that the disruption of positive regulators of muscle hypertrophy (serum response factor and myocardin-related transcription factor A) may result in the development of skeletal muscle atrophy with age." (PMID 33970954, 2021).
cancer (53 papers, 2013 to 2025). A tumor composed of atypical neoplastic, often pleomorphic cells that invade other tissues. "Myocardin-related transcription factor A or megakaryoblastic leukemia 1 (MKL1) is a transcriptional coactivator of serum response factor that has been shown to promote cancer cell migration and invasion." (PMID 32156248, 2021). "MDM4, MRTFA, and WASH5P were each highly up-regulated in embryos of poor morphology and are each in some way implicated in cancer." (PMID 31548358, 2019).
tumor (36 papers, 2013 to 2026). "Morphologically, SRF and IGFBP5 were present in the diffuse-type tumor cells, with some overlap with MRTFA+ cells." (PMID 35087207, 2022). "Here we show that myocardin-related transcription factor A (MRTF-A) plays an important role in myofibroblastic differentiation of primary human MSC in vitro and their tumour-supporting function in vivo." (PMID 31409840, 2019).
neurological disorders (3 papers, 2018 to 2024). "Indeed, lncRNA-SNHG14, MRTFA, and MRTFB play crucial roles in neurological diseases as activators of sero-response factors that regulate related target genes." (PMID 38807051, 2024).
myopathy (1 paper, 2023). A disease of the muscle in which the muscle fibers do not function properly. "Further investigations are required into the molecular mechanisms that regulate WAVE2 expression and the MRTFA–SRF axis in healthy and myopathy animal models to enhance understanding of the complex regulatory networks governing skeletal myogenesis." (PMID 38201213, 2023).
MRTFA also shares sentences with these, for which no sentence is quoted: gastric cancer (9 papers); lung carcinoma (8); fibrosis (6); colitis (5); colorectal cancer (5); megakaryoblastic leukemia (5); pulmonary hypertension (5); autism spectrum disorder (4); diabetic nephropathy (4); Down syndrome (4); liver cancer (4); non-small cell lung carcinoma (4); pancreatic cancer (4); breast tumor (3); cervical cancer (3); diabetes (3); dissection (3); glioblastoma (3); infection (3); liver diseases (3); myocardial infarction (3); ovarian carcinoma (3); Sepsis (3); thyroid cancer (3); abdominal aortic aneurysm (2); aortic aneurysm (2); Aortic dissection (2); basal cell carcinoma (2); breast invasive carcinoma (2); cardiac disease (2).
A further 96 diseases each share a sentence with MRTFA in 2 papers or fewer.